TFRC (transferrin receptor)
Diseases named in the same sentence as TFRC in open-access papers (continued):
Sharing a sentence is not in itself a finding about the gene and the disease.
brain diseases (5 papers, 2022 to 2025). "Increased interest in immunotherapy of brain disorders has prompted the development of different strategies to increase antibody delivery to the brain, including the use of the transferrin receptor (TfR) as a shuttle for therapeutic proteins and antibodies across the blood–brain barrier (BBB)." (PMID 35501533, 2022).
central nervous system disease (4 papers, 2017 to 2024). "In the context of central nervous system disorders, our approach enables the production of HGF mimetics capable of crossing the blood-brain barrier by utilizing an anti-transferrin receptor antibody as a scaffold for LG." (PMID 39108737, 2024).
infectious disease (4 papers, 2013 to 2023). A disorder directly resulting from the presence and activity of a microbial, viral, or parasitic agent in humans. "Large evidence showed that TFRC can act as a target for infectious diseases because various pathogens use TFRC to enter cells." (PMID 35821227, 2022).
endocrinopathies (1 paper, 2009). "Neither sex, hypertransfusion regimen, years or age at onset of DFO therapy, serum transferrin receptor or ferritin concentration, endocrinopathies, or anthropometric parameters correlated with fractures." (PMID 18505376, 2009).
respiratory disease (1 paper, 2024). "The identification of a TFRC proteoform as a cell surface marker for stem cells in the basal cell compartment of human respiratory epithelium provides another tool for studies of lung cell populations and their respective roles in development, regeneration, and respiratory disease pathology." (PMID 39337350, 2024).
TFRC also shares sentences with these, for which no sentence is quoted: cardiovascular diseases (15 papers); neurodegenerative disease (11); vitamin A deficiency (11); parasitemia (10); acute myeloid leukemia (9); metabolic syndrome (9); depression (8); renal cell carcinoma (8); brain glioma (7); pancreatic ductal adenocarcinoma (7); Zinc deficiency (7); B-cell lymphoma (6); coronary artery disease (6); inflammatory bowel disease (6); astrocytoma (5); chronic lymphocytic leukemia (5); Cognitive impairment (5); influenza (5); acute myocardial infarction (4); bipolar disorder (4); dementia (4); erythroleukemia (4); hematological disorders (4); liver disease (4); myelodysplastic syndrome (4); T-cell leukemia (4); Anxiety (3); breast (3); carotid atherosclerosis (3); cognitive decline (3).
A further 251 diseases each share a sentence with TFRC in 3 papers or fewer.